MMP2 (matrix metallopeptidase 2)
Diseases named in the same sentence as MMP2 in open-access papers (continued):
Sharing a sentence is not in itself a finding about the gene and the disease.
cervical carcinoma (continued). "Thus, downregulation of MMP-2 expression by cinnamon could be regarded as a rational approach towards metastatic disease therapy in cervical cancer." (PMID 20482751, 2010). "Our observations elucidate a biological flow wherein EMT, Matrix Metallopep-tidase 2 (MMP2), and extracellular matrix (ECM) degradation are interconnected, ultimately leading to collagen type VI and exacerbating the prognosis of cervical cancer." (PMID 39202746, 2024). "It was observed that angelol-a significantly suppressed the expression of MMP2 and VEGFA, as well as inhibited cell migration and invasive behavior in human cervical cancer cells." (PMID 38751791, 2024). "It has been demonstrated that HPV16-E6/E7 oncoproteins are involved in the regulation of gene expression of MMPs (MT1-MMP, MMP-2, and MMP-9) and the migration of CaSki and SiHa cervical cancer cells." (PMID 38612895, 2024). "While measuring MMP-2 and MMP-9 activities would undoubtedly provide valuable insights, our current investigation focuses on understanding TIE1's broader impact on the cervical cancer progression." (PMID 38617545, 2024). "Increased MMP2 and MMP9 concentrations correlate with the stage of cervical cancer and the age of the patients." (PMID 36982551, 2023). "This suggests that MEG3 inhibits cervical cancer progression by regulating PI3K/AKT/Bcl-2/Bax/P21 and PI3K/AKT/MMP-2/9 signaling pathways in cervical cancer." (PMID 36890809, 2023). "It has been shown that high expression of NEAT1 increased the proliferation and invasion of cervical cancer cells by targeting cyclin D1, CDK4, AKT/PI3K, and matrix metallopeptidase 2 (MMP2)." (PMID 37310654, 2023). "Piperine has been shown to regulate MMP2, MMP9, TIMP1, and TIMP2 in cervical cancer cells at the gene and protein levels." (PMID 36678600, 2023). "SiHa and HeLa human cervical cancer cell migration can be blocked by ALA (10–80 μM) by the downregulation of VEGF, MMP-2, and MMP-9 expression." (PMID 38068849, 2023). "Fibronectin has been shown to regulate MMP-2 and MMP-9 expression and activity in several cancers, including cervical cancer." (PMID 36982551, 2023). "Based on cell and animal experiments, we concluded that KNTC1 can enhance the invasion, migration, and tumorigenicity of tumor cells via MMP2 and MMP9, providing a basis for the subsequent study of KNTC1 as a target for cervical cancer treatment." (PMID 35389773, 2022). "FN1 upregulation has been reported to activate MMP2 and MMP9 via the FAK and PI3K/Akt pathways, promoting tumor metastasis in lung, gastric, breast, ovarian and cervical cancer." (PMID 36151071, 2022). "The inhibition of the Erk signaling pathway restored the inhibiting role of solamargine which interfered with CXCL3 overexpression, in invasion, migration, and expressions of MMP-2 and MMP-9 in cervical cancer cells." (PMID 36345403, 2022). "NaB alone up-regulated MMP2, MMP7 and MMP9 expression, and promoted the migration and invasion of cervical cancer cells." (PMID 36338704, 2022). "For example, inhibition of DPP8 expression in cervical cancer cells can inhibit cell proliferation, migration, and invasion by affecting the expression of Bax and BCL2, inhibiting the expression of MMP2 and MMP9." (PMID 36172198, 2022). "Further studies demonstrated that this promotion of cell motility by HK2 was probably a result of it inducing FN1, MMP2 and MMP9 expression by activating Akt1 in cervical cancer cells." (PMID 34758823, 2021). "In human cervical cancer cells, knockdown of PTX3 reduced the tumorigenic and metastatic potential by downregulating MMP-2 and -9 activities." (PMID 34912809, 2021). "Evidence also suggests that PTX3 promotes metastasis of cervical cancer and EGF-induced metastasis of HNSCC through upregulation of MMP-2 and MMP-9." (PMID 34917682, 2021). "All of these results further confirm that HK2 induces FN1, MMP2, and MMP9 expression by stimulating Akt1 (p-Akt1) in cervical cancer cells, subsequently enhancing cell motility." (PMID 34758823, 2021).
cervical carcinoma (continued). "All of these results demonstrate that stimulated HK2 expression induces Akt1 (p-Akt1), FN1, MMP2 and MMP9 expression in cervical cancer cells." (PMID 34758823, 2021). "As shown in this study, exogenous expression of HK2 activated Akt1 (p-Akt1) in cervical cancer cells, subsequently enhancing cell motility and tumor metastasis by inducing FN1, MMP2 and MMP9 expression." (PMID 34758823, 2021). "Pentraxin 3 (PTX3), a molecule involved in MMP expression, is a component of innate immunity whose knockdown inhibits MMP-2 and MMP-9, decreasing migration and invasion of cervical cancer cells in vitro and in vivo." (PMID 32455616, 2020). "The level of Bcl-2, MMP-2, MMP-9, Fascin, and Erzin expression was significantly upregulated in cervical cancer cells with LGALS1 overexpression, while converse results were obtained in LGALS1 knockdown cancer cells." (PMID 32047564, 2020). "The aim of this study was to determine plasma levels of M-CSF, MMP-2 and TIMP-2 in comparison to CA 125 and SCC-Ag concentrations in patients with cervical cancer in relation to the control group (healthy subjects)." (PMID 30820752, 2020). "In the present study, the ELISA method was used to measure the plasma concentrations of M-CSF, MMP-2, TIMP-2 in cervical cancer patients." (PMID 30820752, 2020). "Our findings suggest a possible antioncogenic regulating role of 5p and 3p strands, and provide evidence of the possible involvement of MAP2, MMP2, and MPP9 in cervical cancer regulated by miR-34a-5p, miR-34a-3p, miR-34c-5p, and miR-34c-3p." (PMID 30696040, 2019). "In contrast to HPV-negative HNSC samples, HPV-positive tumors showed the same tendency as cervical cancers with respect to the expression of COL5A, MMP2, CLDN7, TAGLN, and AURKB, supporting their possible contribution to virus-induced carcinogenesis." (PMID 30918060, 2019). "It was found that expression of MMP2 and VEGF decreased 48 h after CKD-602 treatment in 3 cervical cancer cell lines (CaSki, HeLa and SiHa)." (PMID 31138113, 2019). "The high expression and activity of MMP-2 and MMP-9 have been recognized to be correlated with HPV presence in cervical cancer and the present results were obtained in HPV positive cervical cancer cells." (PMID 30484490, 2018). "Second, SEMA5A stimulates MMP-2 and MMP-9 to increase the invasive potential of cervical cancer cells." (PMID 29977159, 2018). "MMP-9 specific activity and/or MMP-2 active protein levels were (I) increased in HSIL and cervical cancers when compared to normal control tissues (II) and correlated with increased lymph node metastasis and cancer relapse 22,63." (PMID 30208169, 2018). "We herein determined that expression and activity of MMP-2 and MMP-9 were aberrantly increased, but were significantly decreased by GPNMB siRNA in cervical cancer cells in vitro." (PMID 30484490, 2018). "This study also showed that all cervical cancer-derived cell lines analyzed (CaSki, C-4II, HT-3, ME-180, MS751, and HeLa) expressed high levels of MT1-MMP and MMP-2." (PMID 30208169, 2018). "MMP-2 and MMP-9 have important roles in the development of malignant cervical cancer in animal models and humans." (PMID 29267213, 2017). "Previous studies demonstrated that the expression of MMP-2 and MMP-9 is crucial in cervical cancer metastasis." (PMID 29088748, 2017). "b The expression of MMP-2 and MMP-9 increase in all groups of cobalt chloride (150 μM) treated cervical cancer cells." (PMID 28507454, 2017). "Our findings suggest that HOXA11-AS promotes cervical cancer cell migration and invasion via upregulation of MMP-9, MMP-2, and VEGF." (PMID 27792998, 2016). "Consistent with the results of western blot, Ezrin KD significantly increased E-cadherin expression and decreased Vimentin, MMP-2, and β-catenin expression in HeLa and SiHa cells, suggesting that Ezrin KD inhibited EMT in cervical cancer cells in vitro." (PMID 26933912, 2016).
cervical carcinoma (continued). "In CaSki human cervical cancer cells S100A8/A9 treatment induces apoptosis and inhibits migration of CaSki cells; S100A8/A9 also reduced the expression of matrix metalloproteinase (MMP)-2 in CaSki cells." (PMID 25298751, 2014). "After treating with IL-17A, the expression of MMP2 and MMP9 proteins in cervical cancer cell lines (C33A and Caski) was increased, meanwhile the expression of TIMP-1 and TIMP-2 proteins was decreased." (PMID 25250801, 2014). "Fluorescent immunohistochemistry of MMP-2 and MT1-MMP in invasive cervical cancers and their HPV typing." (PMID 23967226, 2013). "More importantly, an increase in immunochemical-reactive MMP-2 and MT1-MMP was detected in 92% and 100% respectively, of invasive cervical cancer biopsies positive for HPV16 highlighting the involvement of HPV16 in cervical cancer progression." (PMID 23967226, 2013). "Positive MMP-2 and MT1-MMP expression was therefore shown in 92% and 100% respectively of 14 invasive cervical carcinomas with positive HPV16 infection." (PMID 23967226, 2013). "Increased MMPs expression, including MMP-2, MMP-9 and MT1-MMP, has been observed during cervical carcinoma progression." (PMID 22438955, 2012). "In cervical carcinoma, high expression of VEGF-C is accompanied by increased expression of matrix metalloproteinase-2 (MMP-2), which is involved in tumor aggressiveness, resulting in poor prognosis and lower survival rates." (PMID 23344023, 2012). "This TGF-β1 is then processed by either the epithelial cell specific integrin ανβ6 or by MMPs, especially active MMP-2 in complex with MMP-14 and TIMP-2 on the cell membrane of cervical cancer cells at the epithelial cell–stroma border." (PMID 19352388, 2009). "Increased mRNA and protein levels of both MMP-2 and MMP-9 have been detected in breast, colon, pancreatic and cervical cancers." (PMID 15989693, 2005). "Similarly, in cervical cancer cell lines, PTX3 knockdown resulted in reduced expression of key molecules involved in tumor cell migration and invasion, including MMP2, MMP9, and urokinase." (PMID 39594709, 2024). "However, we fully recognize the significance of MMP-2 and MMP-9 in cervical cancer progression and plan to explore their activity in future investigations." (PMID 38617545, 2024). "Similarly, we also discovered that Oct4 promoted p38 phosphorylation level and MMP2 and MMP9 levels in cervical cancer cells, indicating the activation of the p38 pathway." (PMID 38430256, 2024). "Furthermore, in cervical cancer, STK39 significantly enhanced tumor invasion via activating the NF-κB/p38-MAPK/MMP2 signaling pathway." (PMID 37031178, 2023). "It stimulates the expression of MMP-2 and MMP-9 in endometrial and cervical cancers." (PMID 36982551, 2023). "Furthermore, the two oncogenes upregulate matrix metalloproteinase 2 (MMP-2) and matrix metalloproteinase 9 (MMP-9) and induce epithelial-mesenchymal transition (EMT) transcription factors in cervical cancer and head and neck squamous cell carcinoma (HNSCC)." (PMID 35421154, 2022). "Further, we verified the promotional effect of KNTC1 on cervical cancer through in-vivo and in-vitro experiments and speculated that KNTC1 might mediate tumor invasion via MMP9 and MMP2." (PMID 35389773, 2022). "Additionally, MNBE downregulated the mRNA levels of MMP2, FAK, and N-cadherin in all three cervical cancer cell lines." (PMID 36088372, 2022). "S. flavescens inhibits cervical-cancer-cell proliferation and metastasis and induces apoptosis by inhibiting the AKT/mTOR signaling pathway; reducing the expression of Bcl-2, cyclin A and MMP2; blocking the G2/M phase cell cycle; and stimulating Bax and E-calmodulin." (PMID 34680171, 2021). "In conclusion, this study demonstrated that HK2 could activate Akt1 (p-Akt1) in cervical cancer cells, subsequently enhancing cell motility and tumor metastasis by inducing FN1, MMP2, and MMP9 expression." (PMID 34758823, 2021).
cervical carcinoma (continued). "This study demonstrated that HK2 could activate Akt1 in cervical cancer cells, subsequently enhancing cell motility and tumor metastasis by inducing FN1, MMP2 and MMP9 expression." (PMID 34758823, 2021). "MMP-2 and MMP-9 are involved in metastasis due to their ability to degrade collagen type IV of the basement membrane of blood vessels, and their overexpression is related to the progression of cervical carcinoma." (PMID 32455616, 2020). "Additionally, the secretion of MMP-2 and MMP-9 was demonstrated to be involved in the proteolytic events required for tumor migration and metastasis in human cervical cancer." (PMID 31572058, 2019). "In cervical cancer, HOXA11-AS silencing was shown to decrease the expression of matrix metalloproteinase-2 (MMP-2), MMP-9, and vascular endothelial growth factor and increase the number of CD133+CD44+ cells, indicating an increase in the cancer stem cell population." (PMID 31757938, 2019). "Even though MMP proteolytic network alterations are common during the progression of cervical cancer, only upregulation of the expression/activity of MMP-2 (gelatinase A) and/or MMP-9 (gelatinase B) seems to be indicative of a poor prognosis in cervical cancer patients 22,57,58." (PMID 30208169, 2018). "Western blot results showed that MMP-2 protein is expressed in total protein extracts from non-cancerous cervix and cervical cancer biopsies, however the immunoreactivity of the detected bands was around 2-fold more intense in CeCa samples." (PMID 30158710, 2018). "Additionally, we discovered that silencing of RIF1 greatly inhibited migration of cervical cancer cells, and found that downregulation of RIF1 significantly decreased the expression of EMT markers, such as N-cadherin, MMP2 and Integrin-β1." (PMID 29291010, 2017). "Moreover, the active form of STAT3, phospho-STAT3 (p-STAT3), and two identified downstream genes of STAT3, BCL-2 and MMP-2, were consistently suppressed, which demonstrated that STAT3 is a target gene of miR-29b in cervical cancer cells." (PMID 28122338, 2017). "We found that the expression levels of N-cadherin, MMP2 and Integrin β1 were significantly decreased in RIF1 knockdown groups, suggesting that silencing of RIF1 might inhibit migration of cervical cancer cells by inhibiting the EMT signaling pathway." (PMID 29291010, 2017). "However, the expression of PTX3 promotes cervical cancer metastasis and EGF-induced HNSCC metastasis via the up-regulation of MMP-2 and MMP-9." (PMID 28489600, 2017). "Therefore, we focused on MMP-2 and MMP-9 when investigating the molecular mechanism by which PLOD2 reduces the migration and invasion of cervical cancer cells in hypoxic conditions." (PMID 28507454, 2017). "Furthermore, the activity of MMP2 and MMP9 secreted by cervical cancer cells was examined by zymography assay." (PMID 25250801, 2014). "Correlation between HPV16, MMP-2 and MT1-MMP results in cervical cancer tissues." (PMID 23967226, 2013). "In cervical cancer, TSP-2 appears only to be highly co-expressed with MMP-2 (P<0.0001)." (PMID 12189553, 2002). "In cervical cancer, TSP-2 appears only to be co-expressed with MMP-2." (PMID 12189553, 2002). "In cervical cancer, TSP-2 seems to be strongly co-expressed only with MMP-2." (PMID 12189553, 2002). "However, the results obtained from this study suggest that PVT1 could be involved in MMP2 and MMP9 regulation by ALKBH5 in cervical cancer cells." (PMID 37639643, 2023). "MMP-2 plays also an important role in the degradation of ECM in cervical cancer and can also regulate other MMPs as well as components not found in the extracellular matrix, such as cytokines, chemokines, interleukins, and growth factors, adhesion, and growth factor receptors." (PMID 36982551, 2023).
cervical carcinoma (continued). "After silencing DPP8 in human cervical cancer cell lines, G1 phase arrest increased Bax expression, decreased BCL2 expression, inhibited cell proliferation, promoted cell apoptosis, and inhibited the expression of MMP2 and MMP9, reducing cell migration and invasion." (PMID 36172198, 2022). "Furthermore, Western blot analysis was used to detect the expression of N‐cadherin, vimentin, MMP‐2 and MMP‐9 in cervical cancer cells, the results of which showed an up‐regulation in these proteins upon E2F4 silencing or C16orf74 overexpression in the presence of HAND2‐AS1 overexpression (P < .05)." (PMID 32314545, 2020). "Additionally, MMP-2 and MMP-9 expression could also be regulated by histone deacetylases (HDACs), a key enzyme of epigenetic regulation, to affect cervical cancer metastasis." (PMID 30484490, 2018). "In addition, western blot analysis revealed that the pre-treatment of SB203580 and PDTC abrogated the upregulation of MMP2 and MMP9 induced by IL-17A, further demonstrating that IL-17A regulated MMPs expression and invasion of cervical cancer cells via activating p38/NF-κB signal pathway." (PMID 25250801, 2014). "Previous studies have also shown that the expression of MT1-MMP, MMP-2 and TIMP-2 correlated well in most, if not all, cervical cancer cell lines." (PMID 23967226, 2013). "SCs displayed increased expression of MMP-2, MMP-9, and MMP-12 at the protein level after co-cultivation with cervical cancer cells, whereas no change in the expression of these MMPs was detected in HeLa and ME-180 cells, differing from previous report about pancreatic adenocarcinoma cells." (PMID 32064233, 2020). "In all three cervical cancer cells, regardless of whether or not they were positive to any type of HPV, we found degradation bands at 72 kDa, corresponding to the size of MMP-2, although with different intensities among the three CeCa cell lines." (PMID 30158710, 2018). "Interestingly however, the Oct4B isoform has been identified to regulate both MMP2 and MMP9 expression in cervical cancer, suggesting the lack of MMP9 suppression may be due to the fact that Oct4B expression was not specifically suppressed in the current study." (PMID 27390927, 2016).